DICER1 (dicer 1, ribonuclease III)
Diseases named in the same sentence as DICER1 in open-access papers (continued):
Sharing a sentence is not in itself a finding about the gene and the disease.
thyroid cancer (continued). "DICER1 carriers have a 16- to 24-fold increased risk of developing thyroid carcinoma which is thought to be due to biallelic mutations in DICER1 leading to an increase prevalence of benign thyroid nodules which over time acquire additional genetic alterations with malignant progression." (PMID 34599283, 2022). "DICER1 pLOF variants were significantly associated with risks of thyroidectomy (odds ratio [OR], 6.0; 95% CI, 2.2-16.3; P = .007) and thyroid cancer (OR, 9.2; 95% CI, 2.1-34.7; P = .02) compared with controls, but there was not a significant increase in the risk of goiter (OR, 1.8; 95% CI, 0.7-4.9)." (PMID 33630087, 2021). "Furthermore, direct correlation between DICER1 mutations and thyroid cancer has been reported previously." (PMID 34322384, 2021). "Malignant tumors (primarily thyroid carcinoma) were observed in 4 of 25 participants (16%) with DICER1 pLOF variants, which is comparable (by 50 years of age) to the frequency of neoplasms in the largest registry- and clinic-based (phenotype-first) DICER1 studies published to date." (PMID 33630087, 2021). "Interestingly, recent findings of oncogenic miR-146b-5p attenuating miRNA biosynthesis by targeting DICER1 and reducing its expression has been implicated in thyroid cancer." (PMID 32163919, 2020). "To date, Dicer1 syndrome has been associated with pleuropulmonary blastomas, cystic nephroma, rhabdomyosarcoma, multinodular goiter, thyroid cancer, Sertoli–Leydig cell tumor, ovarian sex cord-stromal tumor, ciliary body medulloepithelioma, pituitary blastoma, pineoblastoma and other neoplasms." (PMID 33007856, 2020). "Moreover, our three cases are distinct from poorly differentiated thyroid carcinoma of childhood and adolescence, a recently reported entity characterized by DICER1 mutations as well." (PMID 32507920, 2020). "Pathogenic variants in the DICER1 gene cause the DICER1 syndrome, including benign or malignant tumors of the thyroid, kidney, ovary, brain, and lung, but the variant chr14:95570153T/C discovered in our study is not located in a conserved domain; therefore, it may not affect the function of protein." (PMID 35625741, 2022). "However, it is also important to note that the risk of developing thyroid carcinomas secondarily to thyroid nodules has been suggested to be small, and the cumulative incidence of thyroid cancer in carriers of DICER1 variants remains unknown." (PMID 34552563, 2021). "However, the effects of partial or complete Dicer1 loss in thyroid cancer remain unclear." (PMID 41002430, 2025). "In recent studies, we and others identified that DICER1 was the direct target gene of GABPA in thyroid carcinoma cells, and many miRNAs were positively correlated with GABPA expression." (PMID 40813762, 2025). "Our findings deepen the understanding of Dicer1’s role in thyroid cancer, demonstrating that both complete elimination and overexpression of Dicer1 inhibit thyroid oncogenesis, highlighting Dicer1 as a promising target for novel therapeutic strategies." (PMID 39409030, 2024). "In order to study the role of Dicer1 in thyroid cancer, we carried out heterozygous Dicer1 deletion in the TPC1 cell line via CRISPR-Cas9 and we were able to generate three Dicer1 (+/−) cell lines with partial inactivation of Dicer1." (PMID 39409030, 2024). "Given the important role of Dicer1 in miRNA biogenesis and the known role of miRNA in thyroid tumorigenesis, these observations suggested a potential role for this protein in thyroid cancer." (PMID 39409030, 2024). "Interestingly, a recent study reported that the frequency of DICER1 hotspot mutations in thyroid nodules with indeterminate cytology was 1.4%, occurring in a proportion of adult patients and appearing mutually exclusive with alterations in other thyroid cancer-related genes." (PMID 38252873, 2024).
thyroid cancer (continued). "In brief, the 26 DICER1-mutated thyroid lesions include 3 TFND cases, 8 benign/low-risk lesions (7 FTA and 1 NIFTP), 10 well-differentiated thyroid carcinomas (10 FTC), and 5 high-grade thyroid carcinomas (3 DHGTC and 2 PDTC)." (PMID 38637342, 2024). "Demographic and histopathological features of pediatric thyroid cancers with DICER1 RNase IIIb domain alterations." (PMID 36896180, 2023). "Some miRNAs included in these panels, such as mir-146b-5p and mir-31-5p, are consistently increased in malignant thyroid disease but found to be markedly reduced in DICER1-mut DTCs based on data from this study as well as the Thyroid Cancer TCGA." (PMID 36896180, 2023). "This suggests that enoxacin promotes the restoration of DICER1 activity in DICER1-impaired cells, e.g., human thyroid cancer cells." (PMID 35804828, 2022). "As cell differentiation is disrupted along thyroid cancer progression and DICER1 is downregulated in thyroid cancer, we next examined the possible transcriptional regulation of DICER1 by NKX2-1 by assessing the functionality of NKX2-1 over the DICER1 promoter." (PMID 33176626, 2021). "We recently showed that DICER1 acts as a tumor suppressor in thyroid cancer, as its downregulation promotes proliferation, migration, and invasion." (PMID 33176626, 2021). "As the expression of these transcription factors is markedly diminished in thyroid cancer, our findings suggest that DICER1 downregulation in this cancer is mediated, at least partly, through impairment of its transcription." (PMID 33176626, 2021). "We recently demonstrated that DICER1 downregulation in thyroid cancer cells correlates with an increase in proliferation, migration, and invasion." (PMID 33176626, 2021). "Some recent publications, in which the NGS platform was used, documented somatic DICER1 mutations in OCA, and the aggressive subtypes of thyroid cancers PDTC and ATC." (PMID 35008368, 2021). "Given the crucial role of DICER1 in thyroid cancer aggressiveness, the present study was designed to uncover the transcriptional mechanisms that control its expression." (PMID 33176626, 2021). "We studied the expression of NKX2-1, PAX8, and DICER1 in the three thyroid cancer cell lines concurrently." (PMID 33176626, 2021). "As our clinical samples showed a positive correlation between GABPA mRNA expression and DICER1 mRNA expression in thyroid cancer tissues, we sought to explore the relationship between these in FTC cell lines." (PMID 32163919, 2020). "We observed that DICER1 levels were decreased in several cancer types, and thyroid cancer showed the third greatest change in DICER1 expression overall when compared with normal tissue (normal tissue n = 59, tumor samples n = 501)." (PMID 30967628, 2019). "We show that the most overexpressed miRNA in thyroid cancer, miR-146b, targets DICER1, inhibiting its expression." (PMID 30967628, 2019). "In summary, our work reveals some key aspects on the regulation and function of DICER1 in thyroid cancer." (PMID 30967628, 2019). "The expression levels of DICER1 were lower in a panel of thyroid cancer cells than in the control Nthy-ori cells." (PMID 30967628, 2019). "Paradoxically, DICER1 is downregulated in thyroid cancer through the upregulation of targeting miRNAs, particularly miR-146b." (PMID 30967628, 2019). "To further explore the implications of DICER1 dysregulation in thyroid cancer, we sought to study its correlation with aggressive clinical features." (PMID 30967628, 2019). "The clinical relevance of DICER1 repression in thyroid cancer was analyzed in tumor samples and normal tissues using data acquired from TCGA FireBrowse portal and the Morpheus tool." (PMID 30967628, 2019).
thyroid cancer (continued). "A significantly reduced DICER1 level was also observed in thyroid cancer (THCA)." (PMID 40127989, 2025). "Here, we focus on aberrant DICER1 expression in leukemia and thyroid cancer." (PMID 40127989, 2025). "Therefore, in this study, we evaluated the impact of partial or complete inactivation of Dicer1 on thyroid cancer progression using a RET/PTC3 transgenic mouse model of PTC." (PMID 41002430, 2025). "Until now, the spectrum of thyroid alterations associated with constitutional pathogenic variants in DICER1 has included TFND, differentiated thyroid carcinoma, sometimes combining high-grade areas (tumor-in-tumor pattern) and poorly differentiated thyroid carcinoma (PDTC)." (PMID 40892116, 2025). "In addition, we found mutations associated with increased risk of thyroid cancer: three cases harbored alterations of APC (three cmvPTC) and two cases harbored biallelic mutations of DICER1 (one fvPTC and one FTC)." (PMID 35015563, 2022). "A genome-first approach study of the DICER1 observed that individuals harbouring putative LOF variants of DICER1 had a significantly stronger association with thyroid cancer and thyroidectomy compared to matched controls without DICER1 variations." (PMID 34552563, 2021). "Accordingly, the decrease in DICER1 levels in patients with thyroid cancer could be explained by the dedifferentiation events occurring in tumors." (PMID 33176626, 2021). "DICER1 acts as a novel tumor suppressor and is downregulated in thyroid cancer; however, the mechanism of this downregulation and its transcriptional regulation in the thyroid gland is unknown." (PMID 33176626, 2021). "DICER1 silencing decreased PAX8 expression and, importantly, the expression and activity of the sodium iodide symporter, which is essential for the diagnostic and therapeutic use of radioiodine in thyroid cancer." (PMID 33176626, 2021). "The existence of a positive feedback loop between NKX2-1 and DICER1 might have important implications in thyroid cancer, as is supported by the positive correlation between both proteins in a series of patient samples analyzed here." (PMID 33176626, 2021). "We also found that low DICER1 levels in thyroid carcinomas correlate with a worse clinical outcome." (PMID 33176626, 2021). "In terms of gene products most frequently targeted by the differentially expressed miRNAs, the top 30 most affected validated genes included MDM2, CDK6, DICER1, CCND1 (encoding cyclin D1), and CDKN1A (encoding p21), all exhibiting some association to the development or progression of thyroid cancer." (PMID 34676499, 2021). "A familial approach to investigate the risk of thyroid malignancy in DICER1 syndrome patients revealed a 16-fold higher risk of development of thyroid cancer when DICER1 is mutated compared to non-mutated patients." (PMID 33218058, 2020). "Since miR-146b is both produced by and regulates DICER1, this mutual feedback relationship allows for a low level of DICER1 in thyroid cancer but not its complete loss, and thus sufficient DICER1 levels are maintained for cell survival and growth." (PMID 30967628, 2019). "Furthermore, the 3′UTR of DICER1 also contains putative binding sites for other upregulated miRNAs (miR21, -222, -221, -182) in thyroid cancer." (PMID 30967628, 2019).
thyroid cancer (continued). "Our series confirmed that somatic DICER1 mutations have never coexisted with the most common driver mutations in thyroid cancer." (PMID 30956758, 2019). "Overall, these results show that the 3′UTR of DICER1 contains putative binding sites for the most highly overexpressed miRNAs (miR-21-3p, miR-21-5p, miR-221-3p) and that miR-146-5p directly targets DICER1, mediating the potential oncogenic effects and aggressiveness of thyroid cancer cells in vitro." (PMID 30967628, 2019). "Conceptually, some of the present data may seem paradoxical, as DICER1 is downregulated in thyroid cancer, but some miRNAs are upregulated." (PMID 30967628, 2019). "One previous report found two TCGA thyroid cancers that harbored DICER1 somatic hotspot variation." (PMID 30672147, 2019). "Moreover, the present work provides functional evidence that DICER1 acts as a strong tumor suppressor in thyroid cancer, confirming data in other tumor types." (PMID 30967628, 2019). "With this information, we aimed to study the function and regulation of DICER1 in thyroid cancer, and to test whether its impaired function resulted in global miRNA downregulation contributing to a more aggressive phenotype." (PMID 30967628, 2019). "Although somatic DICER1 mutations have not been extensively studied in thyroid cancer, it is accepted that they are driver events." (PMID 30956758, 2019). "However, because global downregulation of miRNA expression and corresponding DICER1 repression appears to play a role in thyroid cancer, restoration of their levels or enhancing miRNA biogenesis might represent an attractive approach in cancer therapy." (PMID 30967628, 2019). "Moreover, we confirmed our findings with TCGA data, in which cases harboring DICER1 mutations in the RNase IIIb domain never coexisted with other well-known driver mutations in thyroid cancer." (PMID 30956758, 2019). "However, in the TCGA data, we did not observe any pathogenic variation in DICER1 in the germline sequence for thyroid carcinoma; we did observe a LP (nonhotspot missense) variant in one participant with a thyroid carcinoma." (PMID 30672147, 2019). "We have recently identified that DICER1, an endoribonuclease responsible for miRNA maturation, is the GABPA target gene in thyroid cancer (TC) cells, and many miRNAs were positively correlated with GABPA expression in primary TC tumors." (PMID 40813762, 2025). "DICER1 has been found to share a regulatory transcription factor with TERT in vitro, based on investigations conducted on thyroid cancer." (PMID 39857323, 2025). "Therefore, the designation DICER1-associated well-differentiated thyroid carcinoma/tumor has been proposed, depending on whether or not they are accompanied by invasive characteristics, respectively." (PMID 40892116, 2025). "We confirmed this downregulation in nine PTCs and their adjacent tissues and showed that the thyroid cancer-derived cell lines TPC1 and BCPAP present very low levels of Dicer1." (PMID 39409030, 2024). "DICER1 gene should be screened in all patients with PPB and considered in other tumors mainly in thyroid neoplasms (multinodular goiter, thyroid cancer, adenomas), ovarian tumors (Sertoli-Leydig cell tumor, sarcoma, and gynandroblastoma), and cystic nephroma." (PMID 33552988, 2020). "In addition, the lack of pathogenic germline variation in DICER1 in the TCGA study thyroid carcinoma samples may be attributable to its focus on sporadic (and adult) rather than familial cancers." (PMID 30672147, 2019). "Although most DICER1-related thyroid lesions are non-cancerous, there have been observations of their presence in thyroid carcinomas, which can vary in their level of differentiation from well differentiated toward a very aggressive phenotype." (PMID 39857323, 2025).
thyroid cancer (continued). "These abnormally expressed 3p miRNAs, which are otherwise low or absent in DICER1-wt DTC and non-neoplastic thyroid tissues, make up exceptional markers for malignant thyroid tumors harboring DICER1 RNase IIIb mutations." (PMID 36896180, 2023). "More recently, a family study reported differentiated thyroid cancer and MNG in six individuals from a family with DICER1 pathogenic mutations and no history of chemotherapy." (PMID 35255942, 2022). "For instance, DICER1, a ribonuclease functioning in the microRNA (miRNA) processing machinery, is transcriptionally activated by GABPA through which the invasive phenotype and metastasis of thyroid cancer are inhibited." (PMID 35549739, 2022). "DICER1, NKX2-1, PAX8, and CREB expression levels were evaluated by gene and protein expression in vitro and by interrogation of The Cancer Genome Atlas (TCGA) thyroid cancer data." (PMID 33176626, 2021). "Because the maturation of most miRNAs is blocked in the absence of DICER1, we analyzed the global expression of the miRNAs differentially expressed in thyroid cancer." (PMID 30967628, 2019). "In this study, we profiled the miRNA (n=2,083) and mRNA (n=2,559) transcriptomes of 20 non-neoplastic, 8 adenomatous and 60 pediatric thyroid cancers (13 follicular thyroid cancers [FTC] and 47 papillary thyroid cancers [PTC]) of which 8 had DICER1 RNase IIIb mutations." (PMID 36896180, 2023). "However, no study had examined the relationship between DICER1 and differentiation in thyroid cancer." (PMID 33176626, 2021). "In the past few years, several studies reported DICER1 biallelic inactivation at the somatic level, predominantly in WDTC, lacking genetic alterations of established thyroid cancer driver genes, strongly suggesting that DICER1 mutations may trigger the onset of specific subgroups of thyroid tumors." (PMID 38252873, 2024).